BRCA2 (BRCA2 DNA repair associated)
Diseases named in the same sentence as BRCA2 in open-access papers (continued):
Sharing a sentence is not in itself a finding about the gene and the disease.
pancreatic cancer (continued). "Pancreatic cancer is currently the only additional malignancy for which there is unequivocal evidence for increased risk in BRCA1 and BRCA2 carriers, although the absolute risk is small." (PMID 17213823, 2007). "Male tumors related to BRCA1 and BRCA2 include breast, melanoma, stomach, prostate, colon and pancreatic cancer." (PMID 17254323, 2007). "Homologous recombination deficiency (HRD) arising from BRCA1or BRCA2 or PALB2 mutations confers sensitivity to platinum chemotherapy and PARP inhibition in pancreatic cancer (PC) and may enable prolonged disease control with immune checkpoint blockade (ICB)." (PMID 41882405, 2026). "The tumor suppressor breast cancer 2 (BRCA2) underlies hereditary breast and ovarian cancer (HBOC) syndrome, conferring a high risk of developing several cancers, including breast, ovarian, and pancreatic cancer." (PMID 39893637, 2025). "The pancreatic cancer SIR was elevated in BRCA2 PV carriers (SIR, 5.72 [95% CI, 2.09 to 12.5])." (PMID 39475295, 2025). "Six cases of BRCA1/BRCA2 double heterozygotes were diagnosed with cancers outside of the usual spectrum of breast, ovarian, prostate and pancreatic cancers; three had colorectal cancer, one with gastric cancer, one with endometrial cancer and another with cervical cancer." (PMID 39843919, 2025). "Genetic syndromes, such as those resulting from inherited mutations in genes like STK11, BRCA1, BRCA2, PALB2, CDKN2A, and DNA repair genes, notably elevate the risk of pancreatic cancer, particularly in individuals with a family history of pancreatic cancer among first-degree relatives." (PMID 39949443, 2025). "Hence, we report that platinum-based anticancer agents and poly ADP ribose polymerase inhibitors were effective against pancreatic cancer bearing BRCA2 p.I3169M fs*48." (PMID 37956396, 2024). "The estimated absolute risks for pancreatic cancer in ATM PTV carriers (11% in males and 8% in females by age 85) are notably higher than for other major pancreatic susceptibility genes including BRCA2, CDK2NA, and PALB2, although the confidence limits are wide." (PMID 39209703, 2024). "Olaparib is also approved to treat germline BRCA-mutant pancreatic cancer and, consistently, RTx-161 significantly reduced cellular resistance to Olaparib in the pancreatic cancer cell line CAPAN-1, which harbors the BRCA2 6174delT pathogenic deletion mutation and loss of the wild-type BRCA2 allele." (PMID 38580648, 2024). "A previously reported BRCA2 missense variant (p.Ile2296Leu) was identified in one pancreatic cancer patient but not in 200 healthy controls." (PMID 37951914, 2023). "APC, BRCA2, BUB1B, ENG and MSH6 were associated with cancer predisposition, and pathogenic/likely pathogenic (P/LP) variants occurred in 6% [pancreatic cancer (4/72); all-cancer (5/90)] and 54% (49/90) carried only variants of uncertain significance (VUS) among cancer patients." (PMID 36896836, 2023). "The pancreatic cancer risk for female relatives of BRCA2 carriers was marginally but not significantly higher than female relatives of non-carriers (RR = 2.54, 95% CI = 1.02-6.30; P = 0.055)." (PMID 36861435, 2023). "It is clinically important to note that a minority of pancreatic cancer patients with germline mutations in BRCA1/BRCA2 and other DDR genes have no family history of cancers." (PMID 36975505, 2023). "For non-cancer individuals, carriers of a BRCA1 or BRCA2 pathogenic variants was recommended to take more intensive screening and preventive strategies for breast, ovarian, prostate and pancreatic cancer." (PMID 38274092, 2023). "A recurrent BRCA2 protein truncating variant (p.Lys3326Ter) was detected in two pancreatic cancer patients but not in 200 controls from Pakistan." (PMID 37951914, 2023). "A novel BRCA2 missense variant (p.Glu2650Gln) was identified in one pancreatic cancer patient but not detected in 200 healthy controls." (PMID 37951914, 2023).
pancreatic cancer (continued). "A similar randomized phase II trial of maintenance olaparib in resected pancreatic cancer and pathogenic BRCA1/BRCA2 or PALB2 mutations (ECOG-ACRIN EA2192, APOLLO) is enrolling patients with either germline or somatic mutations who have received 3 to 6 months of peri-operative chemotherapy." (PMID 36975505, 2023). "This associated risk has been established across other cancers, including pancreatic cancer, where BRCA2 mutations pose a relative risk of 3.5–10 compared to non-carriers." (PMID 35668531, 2022). "The strongest synergistic effect could be seen in the BRCA2 proficient pancreatic cancer cell line CAPAN1 BRCA2/CIN with CI values of 0.1 at a high fraction of cells affected." (PMID 36358659, 2022). "Somatic mutations of BRCA1, BRCA2 and PALB2 are ~14% in pancreatic cancer." (PMID 35328658, 2022). "Male BRCA2 carriers are more frequently affected by breast (OR, 5.47; 95% CI, 4.06–7.37; p < 0.001) and prostate (OR, 1.39; 95% CI, 1.09–1.78; p = 0.008) cancers and pancreatic cancers (OR, 3.00; 95% CI, 1.55–5.81; p = 0.001)." (PMID 35454911, 2022). "Of 135 patients with advanced pancreatic cancer (stages III and IV) eligible for systemic treatment, 76 (56%) were treated with FOLFIRINOX, 35 (25%) were treated with gemcitabine-based therapies, and one BRCA2 mutated patient received olaparib." (PMID 35948602, 2022). "Pancreatic cancer patients with a family history of pancreatic cancer have a higher prevalence of BRCA2 gene mutation than pancreatic cancer patients without a family history of pancreatic cancer (17–19% vs. 5–10%, respectively)." (PMID 35884779, 2022). "In this study, a total of 154 patients had germline BRCA1 or BRCA2-mutated metastatic pancreatic cancer without disease progression during at least 16 weeks of first-line platinum-based chemotherapy." (PMID 35228986, 2022). "Mutation in BRCA1 does not substantially increase the risk of developing pancreatic cancer, but BRCA2 mutations are the most common genetic risk factor for pancreatic cancer with a relative risk of 3.5." (PMID 36500723, 2022). "Frequency of these mutations in GI tumors are still being elucidated but appear at a wide range dependent on the mutation and GI tumor (i.e., BRCA1 pancreatic cancer = 1.3–1.4%; BRCA2 pancreatic cancer = ~3%; BRCA1 biliary tract cancers = 1%; BRCA2 biliary tract cancers = 2%; etc.)." (PMID 36230726, 2022). "BRCA2 accounted for all 2 patients (100%) in 14 pancreatic cancer patients." (PMID 33649982, 2021). "In pancreatic cancer, the early onset risk could be due to high risk genes such as CDKN2A, BRCA1, and BRCA2, or some known rare genes, while the second peak at age 40–49 matches the age of onset of Lynch syndrome." (PMID 34503195, 2021). "In 2005, two efforts highlighted the synthetic lethal interaction between PARP1 inhibition and loss of BRCA1 or BRCA2, which lead to the development of approved clinical PARP inhibitors in ovarian, breast or pancreatic cancer treatments in case of BRCA1 or BRCA2 loss-of-function." (PMID 34439361, 2021). "In a KRAS-driven pancreatic cancer mouse model, germline BRCA2 heterozygous mutation promoted tumor formation with no loss of wild-type BRCA2 allele." (PMID 34283091, 2021). "Interestingly, pancreas cancer was also more frequent in double heterozygotes of a BRCA1 pathogenic variant and BRCA2 c.9976A>T variant, suggesting a potential genetic modifier effect." (PMID 33672545, 2021).
pancreatic cancer (continued). "The BeSHG guidelines propose to discuss the arguments in favor of and against pancreatic cancer screening with BRCA1 carriers if they have ≥1 first-degree relative with pancreatic cancer and with BRCA2 carriers if they have ≥1 first-degree or ≥2 second-degree relatives with pancreatic cancer." (PMID 32655641, 2020). "Notably, however, mutations in the DDR system, including BRCA1 and BRCA2, but also ATM and PALB2, are emerging biologic targets for therapy in advanced pancreatic cancer." (PMID 33198203, 2020). "Familial pancreatic cancer mutations residues are located mostly on BRCA1, BRCA2, p16, PALB2 genes." (PMID 32774122, 2020). "A strong association between pancreatic cancer and BRCA1 and BRCA2 mutations is documented." (PMID 33198203, 2020). "In addition, BRCA2 upregulation has been shown to promote HR DNA repair and radioresistance in pancreatic cancer cells." (PMID 32404140, 2020). "Similarly, RAD521–209 expression rescued the viability in BRCA2−/− CAPAN-1 pancreatic cancer cells, which was reduced approximately 4-fold by treatment with RAD52 shRNA." (PMID 33275133, 2020). "However, Brca1 and Brca2 are also involved among the most common genetic lesions in familial pancreatic cancer patients." (PMID 31480737, 2019). "One study found that mice with conditional germline homozygosity for Brca2 truncating mutations led to developing PanINs at five months of age, and 15% of the mutant mice progressed to pancreatic cancer at 15 months of age without Kras activation." (PMID 31480737, 2019). "Thus, we expected chromosomal instability and hypersensitivity of primary tumor cells isolated from Palb2-KPC, Brca1-KPC, or Brca2-KPC pancreatic tumors to DNA damaging agents." (PMID 31877165, 2019). "Thus, we generated mouse models of pancreatic cancer by inactivation of Palb2, Brca1 or Brca2 genes specifically in the pancreas and compared the resulting tumor latencies, histo-pathologies, anticancer drug responses and immune cell infiltration." (PMID 31877165, 2019). "The first patient who developed MDS had a known BRCA2 mutation and had obtained no prior systemic therapy for pancreatic cancer." (PMID 28454122, 2017). "At the moment the very high risk groups for pancreatic cancer are still patients of AJ descent, as approximately 1.1% of the Jewish population carry a BRCA1 founder mutation and 1.1% carry a BRCA2 founder mutation, and families with ≥ 3 first- or second-degree relatives with PDAC." (PMID 29069866, 2017). "The exome sequencing of a large set of patients with familial pancreatic cancer demonstrated that inherited pancreatic cancer is highly heterogeneous: in these patients, germline mutations of ATM, BRCA2, CDKN2A and PALB2 are observed, all elevating risk of developing pancreatic cancer." (PMID 29156578, 2017). "Of the 64 pancreatic cancer samples where it was possible to obtain a result, one (1.6%) individual carrying the BRCA2 c.156_157insAlu mutation was identified and none was a carrier of the BRCA1 c.3331_3334del mutation." (PMID 27532258, 2016). "It seems that BRCA2 is a high-risk factor for pancreatic cancer development but has not been related to patient outcome or treatment response." (PMID 27689078, 2016). "This hypothesis was tested first in vitro applying a BRCA2 gene knockout (KO) model of the colorectal cancer cell line DLD1 and a BRCA2 gene complementation model of the BRCA2-mutant pancreatic cancer cell line CAPAN1." (PMID 26843614, 2016). "The BRCA2 gene might also be involved in the observed aggregations of pancreatic cancer with other cancers (for example, breast, prostate)." (PMID 19826425, 2009).
pancreatic cancer (continued). "Similarly in pancreatic cancer models, MK-8776 was observed to radiosensitise HR-proficient cell lines, whereas this had no significant influence on BRCA-2 deficient Capan-1 cells, indicating a role for HR in the radiosensitising mechanism." (PMID 39994186, 2025). "DNA damage repair deficiency, for example, through BRCA1/BRCA2, ATM or PALB2 loss, is seen in ∼15% of all pancreatic tumours and may represent a window of opportunity for radiotherapy in these patients due to increased radiosensitivity as a result of genomic instability." (PMID 38979684, 2024). "Consequently, BRCA1 and BRCA2 emerge as the predominant contributors to familial pancreatic cancer." (PMID 38809921, 2024). "Indeed, the pancreatic cancer risk was significantly increased in male relatives of BRCA2 carriers (RR = 4.34) but not relatives of BRCA1 carriers." (PMID 36861435, 2023). "Based on the available literature, it is estimated that 17 to 25% of pancreatic cancer harbor somatic PVs in one of the genes involved in DDR, mainly those implicated in homologous recombination DNA damage response and repair (HR), such as BRCA1, BRCA2, ATM, PALB2, ATRX, and RAD51." (PMID 35563100, 2022). "Due to the particular sensitivity of BRCA2-deficient cells to both olaparib and TRAIL, and the recent evidence on the influence of PARP-inhibition on apoptosis, we aimed at assessing the effect of combined treatment with olaparib and TRAIL in pancreatic cancer." (PMID 36358659, 2022). "Like BRCA1 and BRCA2 mutations, PALB2 mutation may increase the risk of pancreatic cancer." (PMID 35779338, 2022). "Our results provide a preclinical rationale for the combination of PARP inhibitors and TRAIL receptor agonists independent of BRCA2 mutation status in pancreatic cancer and may extend the limited applicability of PARP inhibitors in this disease." (PMID 36358659, 2022). "Our results suggest a potential new combination therapy of olaparib and TRAIL for pancreatic cancer independent of BRCA2 mutations and may extend the limited applicability of PARP inhibitors in this disease." (PMID 36358659, 2022). "Studies by Chang et al17 and Grant et al18 showed that no significant BRCA2 susceptibility was found in the population of China after comparing the variations of pancreatic cancer susceptibility genes with those obtained from a large sample study in Europe using a whole-exome association analysis." (PMID 35171259, 2022). "Capan1 is a BRCA2-deficient pancreatic cancer cell line as a negative control." (PMID 33922657, 2021). "MGPTs generally cover at least 10 common HR-related genes such as ATM, BARD1, BRCA1, BRCA2, BRIP1, CHEK2, NBS1 (NBN), PALB2, RAD51C, and RAD51D, all of whose germline alterations are associated with BRCAness phenotypes for predisposition to breast, ovarian, prostate, or pancreatic cancer." (PMID 35008774, 2021). "To this end, we used glioblastoma cells proficient (M059K) and deficient (M059J) in DNA-PKcs, as well as pancreatic cancer cells without (BxPC3) and with a naturally occurring 6174delT mutation in one BRCA2-allele accompanied by loss of the wild-type allele (Capan-1)." (PMID 32260562, 2020). "Importantly, the expressions of BRCA2 and Smad4 genes were up-regulated after challenge, which suggested the infection might also inhibit the developing of pancreatic cancer of host." (PMID 30792708, 2019). "However, pancreatic cancer also occurs in melanoma-subordinate syndromes (e.g., BRCA2)." (PMID 28283772, 2017).
pancreatic cancer (continued). "Retrospective multicenter studies with large BRCA1 and BRCA2 patient cohorts and prospective studies reviewing serial follow-up imaging on such patients are needed to further assess the potential benefits of modification to current pancreatic cancer screening guidelines." (PMID 27069714, 2016). "Mutations in the high penetrance genes such as BRCA2, PALB2, p16/CDKN2A, PRSS1, SPINK1, and STK11 correlate with a very high lifetime risk of developing pancreatic cancer and may cause as many as 10% of pancreatic cancers in the US." (PMID 24883056, 2014). "It is presumed that through inactivation of genes involved in maintaining genomic stability (e.g. BRCA2 in models of pancreatic cancer) may promote the stochastic acquisition of genetic and consequent morphologic heterogeneity due to the expected increase in mutation rate." (PMID 24268522, 2014). "In a study sequencing 336 pancreatic cancer specimens, potentially actionable targets were identified in 26% of cases, including alterations in ERBB2, BRCA1 or BRCA2, BRAFV600E, ROS1, and ALK1." (PMID 40227779, 2025). "Of the 6474 patients with pancreatic cancer, 27 (0.4%) had BRCA1 alterations, 108 (1.7%) had BRCA2 alterations, 76 (1.2%) had germline ATM alterations, 25 (0.4%) had PALB2 alterations, and 27 (0.4%) had CHEK2 alterations." (PMID 40361359, 2025). "Patients with operable pancreatic cancer and a methylated BRCA1 and BRCA2 promoter status had a statistically significant poorer outcome as compared with patients with a non-methylated one (p=0.012 and p=0.001, respectively)." (PMID 38577595, 2024). "The reported pancreatic cancer risks in BRCA1 and BRCA2 carriers by the age of 70 years were 1.16% and 4.1% in men." (PMID 38929805, 2024). "Interestingly, we found that pancreatic cancer cells from the murine model we created to first reveal that BRCA2 could violate Knudson's two-hit paradigm also contain high levels of methylglyoxal, and sustain similar types of genome-wide mutation, satisfyingly closing the circle from where we began." (PMID 39711301, 2024). "These pathogenic variations in the BRCA genes, found in families with a background of familial pancreatic cancer (FPC), are commonly located in BRCA1’s EXON10 and BRCA2’s EXON11." (PMID 38809921, 2024). "Additionally, a pancreatic cancer cluster region (PcCCR) was identified as associated with pancreatic cancer (between c.3515 and c.6787), a region which overlaps with BRCA2 OCCR but not BCCR and PrCCR, suggesting a possible common oncogenic mechanism between ovarian and pancreatic tumors." (PMID 38397209, 2024). "For the combination of BC and pancreatic cancer (n = 175), PVs were most frequent in ATM (6.9%, 95% CI 4.0–11.6%) followed by BRCA2 (5.1%, 95% CI 2.5–9.8%)." (PMID 36856935, 2023). "Research into pancreatic cancer has identified frequent changes in BRCA genes, especially in BRCA2, occurring in about 5% of patients." (PMID 36358659, 2022). "In pancreatic cancer, understanding the role of germline testing for BRCA1, BRCA2, and PALB2 in homologous recombination repair has allowed the emergence of poly(adenosine diphosphate-ribose) polymerase inhibitors (PARPi) as a treatment option." (PMID 35668531, 2022). "A prospective study of 5,149 females with BRCA1 or BRCA2 carriers showed a significant 2.4-fold increase in the incidence of pancreatic cancer and the increase in the incidence of pancreatic cancer was similar for BRCA1 (SIR = 2.55) and BRCA2 (SIR = 2.13)." (PMID 34356066, 2021). "We compared the histo-pathology of the pancreatic tumors that developed among Palb2-KPC, Brca1-KPC and Brca2-KPC to those of KPC animals." (PMID 31877165, 2019).